MIR3922 (microRNA 3922)
Synonyms: hsa-mir-3922
Gene: MicroRNA gene on chromosome 12 (104,591,633 to 104,591,716, forward strand). Ensembl gene ENSG00000264295.
Diseases named in the same sentence as MIR3922 in open-access papers:
MIR3922 is named in the same sentence as 4 diseases in open-access papers, as found by Europe PMC text mining. Sharing a sentence is not in itself a finding about the gene and the disease. The quoted sentences say what the papers report.
tumor (1 paper, 2015). "Our findings also potentially reveal an unexpected role for CHST11 and/or MIR3922 as tumor suppressors whose disruption may contribute to malignant lymphoproliferative disease." (PMID 26436107, 2015). "Our findings also support the hypothesis that CHST11 and/or MIR3922, a microRNA whose function has not previously been described, may act as tumor suppressors in the lymphocyte lineage." (PMID 26436107, 2015).
MIR3922 also shares sentences with these, for which no sentence is quoted: lymphoma (1 paper); lymphoproliferative disorder (1); T-cell lymphoma (1).